RHOB (ras homolog family member B)
Diseases named in the same sentence as RHOB in open-access papers (continued):
Sharing a sentence is not in itself a finding about the gene and the disease.
tumor (continued). "RhoB mediates the regulation of various cell biological functions, including cytoskeletal growth, signal identifying, cytosport, apoptosis, neural crest migration, cell motility, and membrane trafficking and has a certain relationship with tumor growth and proliferation." (PMID 31011573, 2019). "Isolating endothelial cells from tumors in the rhoB−/− and rhoB+/+ mice, showed a dose-dependent decrease in p-AKT associated with allelic loss, supporting the idea that RhoB may play competing biological roles in tumor versus endothelial cells." (PMID 29385717, 2018). "However, when assessing tumor progression, the greater number of early lesions initially observed in the rhoB-deficient mice did not result in greater overall tumor burden at the endpoint of the experiment." (PMID 29385717, 2018). "In line with this hypothesis, G594 treatment induced tumor regression in RHOB‐deficient but not in wild‐type mice." (PMID 28003335, 2017). "Interestingly, our in vitro and in vivo results strongly suggest that RHOB is critical for both tumor growth and the apoptotic response to erlotinib, by preventing erlotinib‐induced AKT dephosphorylation and leading to the maintenance of a high level of active AKT." (PMID 28003335, 2017). "Moreover, we analyzed the target small GTPases, RhoG and RhoB, and we found a clear reduction of RhoB in pancreatic cancerous cell lines, but not in non-cancerous pancreatic cells, that correlates with the fact that RhoB protein deletion promoted tumor formation." (PMID 27832197, 2016). "Due to the role of RhoB as a tumor suppressor, that inhibits growth, cell migration, invasion and maintenance of mesenchymal morphology, functioning as a negative modifier in cancer, thus it is evident that a reduction in its level of expression could favor cancer progression 2016;." (PMID 27832197, 2016). "Also, ERM/Rho protein expression did not predict patient survival, but RhoB over-expression in the stromal compartment of the tumours was found to be associated with a better prognosis (P = 0.0106)." (PMID 23420497, 2013). "Moreover, four studies showed an inverse correlation between RhoB expression and tumor grade." (PMID 23339407, 2013). "It has been proposed that RhoB can work as a tumor suppressor as it is activated in response to several stress stimuli including DNA damage or hypoxia, and it has been reported to inhibit tumor growth, cell migration and invasion and have proapoptotic functions in cells." (PMID 20822528, 2010). "Also the amount of RhoB, which has recently been described to interfere with cytostatic drug resistance by influencing apoptotic cell death, is enhanced in tumours." (PMID 12237774, 2002). "RHOB expression positively correlated with IC50 values, promoting the suppression of tumor growth by inducing G2/M cell cycle arrest and increasing apoptosis." (PMID 39941131, 2025). "Computational prediction identified several tumor-suppressor genes, including PTEN, STAT3, RhoB, and PDCD4, as potential direct targets of miR-21-5p." (PMID 41465544, 2025). "Among patients undergoing radiation therapy, RhoB overexpression correlated with elevated FOXM1 levels, advanced tumor, local and distant metastasis, and independently predicted poor survival, irrespective of other clinical factors." (PMID 38355625, 2024). "Rho GTPases, including RHOB, can regulate several pathways related to signal transduction, cell adhesion, tumor cell invasion, and cell division, warranting further future examination of both FOXO1 and RHOB in H3K27M DMGs." (PMID 37094128, 2023). "It is defined as one of the “oncomiRs”, the cancer-promoting miRNAs, and has been documented to target several tumour suppressor genes (such as PTEN, RHOB, PDCD4, TIMP3) and play a role in signalling pathways (RAS/MEK/ERK, PTEN/PI3K/AKT, and Wnt/β-catenin)." (PMID 36140324, 2022).
tumor (continued). "Eight hub genes (CDK1, EGFR, UBC, MYC, CCNB1, RHOB, CDC6, and CDC20) have tumor suppressor functions, while five hub genes (CDK1, EGFR, FYN, UBC, and CCNB1) are protein kinases as well." (PMID 35632527, 2022). "DMA identified 59,654 differential methylation sites between two clusters and part of these sites were correlated with tumor angiogenesis genes including CDH13, COL4A3, and RHOB." (PMID 33761933, 2021). "An inverse correlation was also observed between RHOB expression and FMISO uptake (ρ = −0.46, p < 0.001), indicative of RHOB downregulation in more hypoxic tumours." (PMID 34298725, 2021). "The members of the DLC family have been established as tumor suppressors, with DLC3 shown to localize at RhoB and Rab8 positive endomembranes, in addition to sites of cell-cell and cell-matrix adhesions." (PMID 31766364, 2019). "These contradictory observations suggest that RHOB may have different functions in cancer that are context-dependent and cell-type specific, possibly responding to signals in the tumor microenvironment and that RHOB can function both as an oncogene and a tumor suppressor in cancer." (PMID 31888022, 2019). "Subsequent studies showed that treatment of tumor cells with a FTI leads to a decrease in farnesylated RhoB levels and a corresponding increase in RhoB-GG levels." (PMID 29385717, 2018). "Another step in this process is the small GTPase RhoB, which was recently identified in a genome-wide screen as an important component in BTN3A1-dependent tumor cell recognition by Vδ2Vγ9 T cells." (PMID 28649364, 2017). "As anticipated, miR-21 targeted the largest number of tumour suppressors (n = 14), among which PTEN was additionally targeted by miR-29b and miR-144, while RHOB was also repressed by miR-223." (PMID 27056547, 2016). "A good example is the RHOB gene (ras homolog gene family member B [MIM: 165370]), a tumor suppressor that belongs to the Rho GTPases family." (PMID 26474060, 2015). "On the other hand, miR-21 has been shown to have antiangiogenic functions, targeting RhoB in ECs and TGF-βRII in human adipose-derived stem cells (hADSCs), thus decreasing the tumor vascularity induced by the cells." (PMID 24356956, 2014). "The data presented in this study suggest that trastuzumab properties are complex, but also highlight a significant effect of this agent in the early stages of tumour invasion as a consequence of PTEN and RhoB regulation." (PMID 20588279, 2010). "For example, RHOB (Ras homologue family member B gene) acts as a tumor suppressor most of the time, unlike other members of the Ras homologue family." (PMID 40574864, 2025). "In coherence, the docking analysis of the RhoB protein with 5-FU and OXL showed that modulating the expression of RhoB with OXL might inhibit the molecular interaction between the RhoB and caspase 3 protein to induce apoptosis in tumor cells." (PMID 38355625, 2024). "This analysis indicates that DNp73 expression has the potential to offer more favorable prognostic insights compared to RhoB when employing AI for the analysis of both tumor and biopsy tissues, with or without RT." (PMID 38014709, 2023). "Here, too, it was shown that “simple” RhoB conjugates 1–9 also had lower cytotoxicity than the corresponding triterpenoid analogs, but their tumor cell/non-tumor cell selectivity was also diminished." (PMID 33233650, 2020). "Together these data suggest that LMF/fucoidan could act as an upregulator of RhoB because LMF significantly and dose-dependently upregulated RhoB mRNA levels, supporting the role of RhoB as a tumor suppressor." (PMID 31331053, 2019). "Additionally, we show that the ROCK inhibitor RKI-1447 suppresses ROCK-dependent signaling, tumorigenicity, and invasion by affecting RHOA, RHOB, vimentin, and JUN in vitro and inhibits tumor growth in vivo." (PMID 31888022, 2019).
tumor (continued). "It is somewhat unexpected that the combined deletion of RhoB and p27 leads only to significantly increased tumour volumes compared to p27 deletion alone, but did not significantly increase mean tumour numbers." (PMID 30549261, 2019). "One study closely examined the interaction between miR-19a and RHOB, establishing that human antigen R (HuR) enables miR-19a loading to the 3′-UTR of RHOB; in turn, this binding of the 3’-UTR downregulated expression of the RHOB tumor suppressor." (PMID 31200451, 2019). "The lack of significantly increased tumour numbers indicates that inhibition of RhoB by p27 is surprisingly less important for tumour formation than for tumour growth." (PMID 30549261, 2019). "Similarly, the mechanism of a common tumour suppressor gene, RASSF1A, suppresses invasion and metastasis in NSCLC cell lines through PP2A/RhoB and guanine nucleotide exchange factor H1 (GEF-H1) activity." (PMID 31623614, 2019). "The opposite roles of RhoB in p-AKT regulation suggest contrasting biological function between tumor cells and nontumor endothelial cells." (PMID 29385717, 2018). "Although Rho GTPases RhoA, RhoB, and RhoC share more than 85% amino acid sequence identity, they play very distinct roles in tumor progression." (PMID 29385717, 2018). "This suggests that the re-expression of RhoB alone by inhibiting HDAC expression is not sufficient to promote tumor progression." (PMID 29385717, 2018). "In the GC dataset RHOB was significantly downregulated in tumor samples compared to normal tissues in Asian GC, but not in Caucasian GC tumors." (PMID 27806312, 2016). "We focused our attention on the stress-inducible RHOB gene that plays a negative role on tumor progression." (PMID 26098773, 2015). "We found that fibroblasts irrespective of their RhoB status do not modulate intrinsic radiosensitivity of TC-1 but produce diffusible factors able to modify tumor cell fate." (PMID 25635683, 2015). "DLC1 (Deleted in Liver Cancer 1) gene encodes a RhoGTPase-activating protein (RhoGAP), which exerts most of its tumor suppressor functions through suppression of small Rho GTPases proteins RhoA, RhoB, RhoC and to some degree Cdc42, but not Rac." (PMID 24683532, 2014). "Unlike RhoA, RhoB is often down-regulated in human tumors and expression inversely correlates with tumor aggressiveness." (PMID 24279335, 2013). "The specific functions of RhoB have not been described in detail yet, but experimental studies have shown that RhoB is down-regulated in human tumours and that its expression is inversely related to tumour progression." (PMID 23420497, 2013). "RhoB expression is reduced in several tumour types compared with non-cancer tissues and can contribute to tumour growth by regulating apoptosis." (PMID 22724071, 2012). "Unlike RhoA and RhoC, the level of active-RhoB protein, which is a tumor suppressor gene, was up-regulated in both BxPC-3 and PanC-1 cells by BITC treatment." (PMID 22016776, 2011). "Unlike RhoA and RhoC, RhoB is often downregulated in human tumors and its expression inversely correlates with tumor aggressiveness." (PMID 20822528, 2010). "Indeed, several of the identified genes in our study are reported to be involved in angiogenesis, tumor angiogenesis and arteriogenesis, i.e. IL-8, ET-1, CARP, HPTPη, ID1, MGSA, SMAD7, HO-1, RHOB, PTHLH, SERPINH1/HSP47, JAG1, GNA13 and TEAD4." (PMID 16594992, 2006). "Furthermore, cells isolated from RhoB−/− tumor lesions displayed enhanced anchorage-independent growth and survival compared with cells from RhoB+/− mice, which did not grow at all." (PMID 32992837, 2020). "This suggests that RHOB expression levels determine the efficacy of EGFR signaling and led us to hypothesize that RHOB levels could account for the initial sensitivity of tumor cells to EGFR‐TKI through a mechanism that may involve EGFR‐dependent AKT signaling." (PMID 28003335, 2017).
tumor (continued). "Apoptotic assays after transfection with RhoB siRNA or Control siRNA next to treatment with TSA revealed that RhoB siRNA, yet not Control siRNA, lead to a significant reduction of apoptosis of revived-RhoB tumor cells in contrast to nu-transfected (NT) carcinoma cells." (PMID 24223801, 2013). "Intriguingly, RhoA and RhoB reactivity was found to significantly increase with the proliferation index and grading of the tumours, but the authors did not correlate Rho GTPase expression with clinicopathological parameters, such as nodal status or patient survival." (PMID 23420497, 2013). "We show in this study that RhoB induction in control cell lines (OVCAR-3A and WT) and its inhibition in OVCAR-3LTE is critical in ovarian cell lines we used for migration capacities and certainly for tumour aggressiveness together induced by trastuzumab treatment." (PMID 20588279, 2010). "The exact mechanism whereby RhoB suppresses tumor growth and invasion is not clear, although its role in endosomal trafficking could be important." (PMID 20822528, 2010). "In comparison to a uniform distribution of RHOB in endosomes and at the plasma membrane in A549, the presence of large endosomal clusters of RHOB was visualized by a split-GFP system, suggesting that RHOB rerouting in the PC9 tumor cell could impair the reactivity of the immune response." (PMID 32733462, 2020). "For example, the role of RhoB may be different in hypoxic versus non-hypoxic tumor environments." (PMID 29385717, 2018). "Although tumour grade and stage were related to RhoC and ROCK-1 in ccRCC, they were not related to RhoB." (PMID 21119662, 2011).
cancer (97 papers, 2007 to 2025). A tumor composed of atypical neoplastic, often pleomorphic cells that invade other tissues. "RhoB, a member of the Rho GTPase family, has been implicated in the malignant progression of various cancer types." (PMID 39336777, 2024). "The Ras Homolog Family Member B (RhoB) is a tumor suppressor gene associated with different cancers." (PMID 37345145, 2023). "RhoB was reported as a cancer suppressor and loss of RhoB was strongly associated with poor survival of patients." (PMID 35538494, 2022). "In stark contrast to the oncogenic association of RhoA and RhoC, RhoB has been shown to be significantly downregulated in cancers of various cell origins." (PMID 31200451, 2019). "A decrease in RhoB mRNA levels from aged mouse skeletal muscle and lung tissues proposes the possibility that RhoB loss leads to increased cancer rates with age." (PMID 31200451, 2019). "K-ras mutations, as part of the Ras pathway, likewise decreases RhoB transcription inhibiting the myriad of pathways regulated by RhoB and is linked with worse prognosis in several cancer types." (PMID 31200451, 2019). "A number of reports have indicated that loss of RhoB expression is frequently associated with cancer progression." (PMID 19317917, 2009). "We previously reported the presence of a Variable Number of Tandem Repeat (VNTR) sequence in the human RhoB 5' region that is known to be linked with the penetrance and the development of several cancers." (PMID 18047684, 2007). "A future investigation of the proposed AI approach is to use RhoB-expression tissues of healthy subjects, tumors, and NATs to discover the predictive power of the three tissue types and molecular changes associated with cancer." (PMID 36704244, 2022). "Moreover, the PDE5A gene showed the highest correlation with survival risk, whereas the RHOB gene had the lowest correlation in diverse cancer types." (PMID 34824999, 2021). "RHOB, is a member of small GTPases belonging to the Ras protein superfamily, might have a suppressive activity in cancer progression, in fact its loss occurs frequently in ovary carcinogenesis and progression." (PMID 27259239, 2016). "Notably, RhoB has been implicated in fostering malignant phenotypes across various cancer types." (PMID 39336777, 2024). "RHOB maintains cell-cell adhesion in epithelial-derived cancer cells by regulating the levels and localization of E-cadherin." (PMID 39944833, 2025). "As an important member of the Rho GTPase family, RhoB is thought to be a negative regulator of cancer progression, invasion and metastasis, as its expression is reduced in a number of tumors, including BLCA54–58." (PMID 39521858, 2024). "Subsequently, we found that the knockdown of RhoB inhibited the proliferation, migration, and invasion of cancer cells, while increasing apoptosis." (PMID 39336777, 2024). "The subsequent WB analyses also confirmed the downregulation of RhoB expression in cancer cells compared to that of Hcer-Epic cells." (PMID 39336777, 2024). "Unlike other members of Rho family, like RhoA and RhoC, which play oncogenic roles, RhoB has been shown to suppress tumorigenesis in pancreatic and other cancers." (PMID 37794133, 2023). "Another mechanism of action for the anti-cancer activity of PCA follows the downregulation of the Ras/Akt/NF-kB pathway by targeting activation of RhoB, further leading to a drop in MMP-2-mediated cellular actions in cancer cells." (PMID 36247004, 2022). "RhoB has been reported to be targeted by various miRNAs to regulate apoptosis, proliferation and migration of cancer cells." (PMID 35538494, 2022). "The Rho subfamily of RhoGTPases plays critical roles in physiological and pathological processes of cancers, and consists of three proteins, RhoA, RhoB, and RhoC." (PMID 35538494, 2022). "In PA, miR-19a is upregulated and downregulates Ras homolog family member B (RHOB) to suppress cancer cell apoptosis." (PMID 35387554, 2022).